TINCR (TINCR ubiquitin domain containing)
Diseases named in the same sentence as TINCR in open-access papers (continued):
Sharing a sentence is not in itself a finding about the gene and the disease.
tumor (continued). "The TINCR expression level was reversely correlated to serosal invasion (p = 0.001), lymph metastasis (p = 0.037), and tumour node metastasis (TNM) classification (p = 0.016), while positively correlated with differentiation degree (p = 0.017)." (PMID 27009809, 2016). "Loss of TINCR leads to stress-induced ATF4 activation, immune evasion, and resistance to BRAF/MEK inhibitors in melanoma cells, highlighting its role at the intersection of immune regulation and tumor progression." (PMID 40777108, 2025). "Moreover, lncRNAs such as LINC00346 and TINCR connect ATF4 signaling to tumor immune evasion, revealing their dual roles in both immune homeostasis and cancer immunology." (PMID 40777108, 2025). "In vivo, the combined treatment more effectively inhibited tumor growth than TINCR knockdown did." (PMID 36725842, 2023). "The tumor weight in the TINCR knockdown group was also lower than that in the control group." (PMID 36725842, 2023). "In the subcutaneous tumor model, downstream signaling molecules were downregulated in the TINCR knockdown group relative to the control group, and there were no significant changes in STAT1 and p-STAT1, and the protein levels of PD-L1 and USP20 were also downregulated." (PMID 36725842, 2023). "Additionally, in vivo study showed that PTBP1 promoted tumor-initiating capacity reduced by TINCR depletion." (PMID 36385098, 2022). "Further RT-PCR showed a substantial decrease in miR-375 expression in tumor-bearing tissues of the lncRNA TINCR overexpression group compared to the vector-control group, whereas ATG7 expression was shown to be considerably upregulated in tumor tissues that overexpressed lncRNA TINCR (vector-TINCR)." (PMID 36157234, 2022). "Our finding indicated that there existed a TINCR/miR-195-3p/ST6GAL1/NF-κB signaling regulatory axis that regulated tumor progression and oxaliplatin resistance, which might be exploited for anticancer therapy in HCC." (PMID 34980201, 2022). "It is found that TINCR is required to maintain self-renewal of LCSCs and tumor propagation." (PMID 36385098, 2022). "Here the authors report that TINCR lncRNA encodes pTINCR, a ubiquitin-like protein (UBL) that promotes epithelial differentiation through the SUMOylation and activation of CDC42, and it has tumour suppressor activity in epithelial cancers." (PMID 36369429, 2022). "In cSCC, TINCR lncRNA has been consistently reported to have a tumor suppressor activity." (PMID 36369429, 2022). "Finally, TINCR upregulation slowed xenograft tumour growth in nude mice and significantly increased survival compared with control mice." (PMID 34187411, 2021). "Overexpression of miR-210 was determined to reverse the tumour-suppressive effects of TINCR." (PMID 34187411, 2021). "The in vivo function of TINCR was accessed on survival rate and tumor growth in nude mice." (PMID 34187411, 2021). "Both TINCR and epithelial differentiation-associated genes, including IVL and KRT4, were significantly upregulated during OSCC cell calcium-induced differentiation but were reduced when cell dedifferentiation occurred in tumor spheres." (PMID 33732637, 2021). "It has been reported that TINCR regulates the malignancy of tumours through two mechanisms." (PMID 34187411, 2021). "TINCR has been reported to regulate the malignant process of tumor through two mechanisms." (PMID 33649294, 2021). "Moreover, TINCR expression was higher in advanced tumor-node metastasis (TNM) stages III and IV than in TNM stages I and II." (PMID 33446634, 2021). "In vivo xenograft experiments were conducted to analyze the role of TINCR on tumor growth in vivo." (PMID 32681722, 2020).
tumor (continued). "TINCR depletion increased tumor xenograft growth in vivo, while TINCR overexpression inhibited it." (PMID 32681722, 2020). "However, another study in diverse types of SCC originated from cervix, head and neck and lung implied a tumor suppressor role for this lncRNA as TINCR silencing by siRNA enhanced cell growth and migration of these cells." (PMID 32695943, 2020). "Recently, TINCR was proposed to be involved in tumor progression." (PMID 30853664, 2019). "MiR-7 inhibition severely compromised TINCR silencing-elicited tumor repressive effects." (PMID 29614984, 2018). "The pro-tumor activity of TINCR was further demonstrated in xenograft tumor mouse model." (PMID 29614984, 2018). "Therefore, we consolidated the observation that TINCR-knockdown significantly suppressed tumor growth both in vitro and in vivo." (PMID 29614984, 2018). "Up-regulation of TINCR expression has been demonstrated to remarkably correlate with tumor size, tumor differentiation, TNM stage and vascular invasion, which revealed that TINCR expression was correlated with advanced tumor progression and aggressive clinicopathological features." (PMID 28546230, 2017). "Here we report a novel pathway involved in E2F1 and TINCR in tumor development and GC cell growth." (PMID 28569791, 2017). "In the current study, HCC patients with high TINCR expression had larger tumor size and advanced stage, suggesting that TINCR could be involved in the development and progression of HCC." (PMID 28546230, 2017). "miR-137/miR-133a-TINCR pathway may serve as a promising target for tumor recurrence and prognosis of patients with HCC." (PMID 28546230, 2017). "Taken together, our results indicate that TINCR is a tumour suppressor that, when downregulated, may promote CRC growth and metastasis, and accelerate hydrolysis of EpCAM." (PMID 27009809, 2016). "Therefore, the malignant metastatic potential of tumor cells may be inhibited through downregulation of TINCR expression." (PMID 37051356, 2023). "Moreover, and in support of a differentiation role for TINCR as a tumor suppressor, gene expression analysis of HNSCC patient samples from TCGA14 revealed an association of TINCR RNA levels with transcriptional programs linked with epithelial differentiation and keratinization (, 5)." (PMID 36899004, 2023). "In this study, we report that TINCR encodes an evolutionary conserved ubiquitin-like protein (UBL) that we have named pTINCR, which regulates epithelial differentiation by enhancing the SUMOylation and activation of CDC42, and which acts as a tumor suppressor in epithelial cancers." (PMID 36369429, 2022). "In addition, combined with the clinical data of the patients, we surprisingly found that TINCR expression was not related to those generally recognized risk factors, including tumor size, number, vascular invasion, degree of differentiation (Table." (PMID 34980201, 2022). "The literature has shown that TINCR may exhibit different functions in different tumours." (PMID 34187411, 2021). "Thus, they suggested that TINCR silencing intensely stimulates tumor growth and metastasis." (PMID 32695943, 2020). "TINCR can stabilize mRNA by preventing Staufen-mediated mRNA decay of differentiation genes in epidermal tissue, but it is unclear whether this mechanism plays a role in tumor evolution." (PMID 32231885, 2020). "Microarray analyses revealed several differentially expressed lncRNAs; among them, five novel lncRNAs, TINCR, CCAT2, AOC4P, BANCR, and LINC00857, were detected in tumor tissue samples and pre and post-operative plasma." (PMID 37670949, 2023). "All together, our data show that TINCR activates the transcription of ATG5 by interacting with PTBP1, leading to LCSC self-renewal and tumor propagation." (PMID 36385098, 2022).
tumor (continued). "First, TINCR enhances EGFR expression and downstream signaling via regulation of the STAT3–TINCR–EGFR pathway, and acts as a competing endogenous RNA to upregulate EGFR expression by sponging miRNA-503, resulting in tumor growth, proliferation, and migration." (PMID 35159070, 2022). "In conclusion, TINCR can promote LCSC self-renewal and tumor progression by autophagy activation through PTBP1/ATG5 regulatory pathway." (PMID 36385098, 2022). "Consistent with the in vitro results, TINCR overexpression restricted the growth of TU212 xenografts in nude mice, and the survival of tumour-bearing mice was prolonged." (PMID 34187411, 2021). "TINCR is one of the downstream targets of ZNF750, and it mediates ZNF750 tumour suppression and the expression of important molecules that induce differentiation." (PMID 34187411, 2021). "In a recent study, TINCR was however found to increase in CRC and seemed to work as a sponge for tumor suppressor miR-7." (PMID 32681722, 2020). "TINCR was reversely correlated with CRC progression and promoted tumor cells growth, metastasis in vivo and in vitro." (PMID 27009809, 2016). "Considering that the ceRNA mechanism is one way in which lncRNAs participate in the regulation of tumor progression, we assessed whether USP20 can be regulated by TINCR through the ceRNA mechanism." (PMID 36725842, 2023). "Several studies have compared expression of TINCR between human tumor samples and non-cancerous samples from the same tissues." (PMID 32695943, 2020). "Compared with paired normal thyroid tissues, four lncRNAs (LOC100130238, HAND2‐AS1, MIR9‐3HG, and LOC143666) were downregulated in PTC tumor tissues, whereas the remaining four lncRNAs (EGFEM1P, LINC00284, TINCR, and ABCC6P1) were upregulated in PTC tumor tissues." (PMID 30318850, 2018). "We also analyzed the expression of TINCR in tumour and paired non-tumour tissues obtained from 44 patients with CRC." (PMID 27009809, 2016). "The tissue differentiation of lncRNA induces the involvement of nonprotein coding RNA, TINCR ubiquitin domain containing (TINCR), in tumor progression." (PMID 37051356, 2023). "As aberrant keratinocyte differentiation and stem-cell characteristics are involved in KC tumor development, it is not surprising that the expression of keratinocyte differentiation inducing lncRNAs, SMRT-2 and TINCR, are strongly downregulated in cSCC." (PMID 32462404, 2020).
cancer (42 papers, 2016 to 2023). A tumor composed of atypical neoplastic, often pleomorphic cells that invade other tissues. "Previous studies have showed that TINCR play critical roles in multiple biological processes implicated in the development and progression of cancers." (PMID 33649294, 2021). "Assembling evidences suggested that aberrant expression of TINCR intimately associated with variety of human cancers." (PMID 29614984, 2018). "However, some lncRNAs like TINCR were associated with both good and poor prognosis depending on the cancer type." (PMID 32231885, 2020). "Current reports showed that TINCR had remarkable impacts on cell proliferation, apoptosis, and angiogenesis promotion, therefore regarding as a biomarker which was significantly associated with cancer metastasis and unfavorable prognosis." (PMID 28546230, 2017). "However, whether TINCR also acts as the hallmark of other cancers is still unknown and needed to be studied." (PMID 27586866, 2016). "In conclusion, this research showed that lncRNA TINCR was highly expressed in hepatocellular cell lines and cancer tissues." (PMID 36157234, 2022). "The recently discovered lncRNA TINCR has a crucial role in the initiation and progression of a wide variety of cancers." (PMID 36157234, 2022). "The abundance of TINCR is up-regulated in various cancers, in which it promotes proliferation of the cancer cells." (PMID 34351912, 2021). "In this study, we first detected the expression level of TINCR in cancer tissues by fluorescent quantitative PCR." (PMID 34187411, 2021). "Next, from the CCLE database, TINCR expression was found to be positively correlated with STAT3 expression in human cancer cells." (PMID 33446634, 2021). "Terminal differentiation-induced ncRNA (TINCR) plays an essential role in epidermal differentiation and is involved in the development of various cancers." (PMID 34187411, 2021). "Recently, evidence has accumulated showing that TINCR can actively participate in cancer progression." (PMID 34187411, 2021). "Recent studies have also revealed a role for TINCR in cancer, including breast, lung, liver, esophageal, colon, bladder, prostate, gastric, and oral tumors." (PMID 34351912, 2021). "Our findings broaden the current understanding of the diverse manners in which TINCR functions in cancer biology." (PMID 33446634, 2021). "TINCR has been reported involved in the tumorigenesis of many different human cancers, including CRC." (PMID 32681722, 2020). "Aberration in TINCR expression has been identified in multiple human cancer types, and its aberrant expression has been shown to have significant functions in cancer progression." (PMID 32681722, 2020). "Another lincRNA, TINCR, is involved in normal tissue differentiation and plays a critical role in cancer and metastasis." (PMID 31890219, 2019). "Consistent with the results from clinical samples, TINCR transcripts were significantly higher in cancer cell lines than in immortalized human mammary epithelial cell line MCF-10A." (PMID 29614984, 2018). "Importantly, a defect in the physiologic response to UV exposure potentially links TINCR with pathologies derived from excessive UV-induced skin damage including cancer." (PMID 36899004, 2023). "Importantly, TINCR was described as an oncogene in other cancers, acting as ceRNA for various miRNAs." (PMID 35159386, 2022). "Notably, epithelial-like cancer cell lines expressed higher levels of TINCR compared to mesenchymal-like cancer cell lines." (PMID 36369429, 2022). "Notably, it is reported that TINCR exerts opposite roles in the pathogenesis of different human cancers." (PMID 36385098, 2022). "Given the potential widespread impact of TINCR and its downstream molecules, an improved understanding of how TINCR mediated sialylation controls cancer cell biology may give new horizons to a range of HCC therapeutics." (PMID 34980201, 2022).
cancer (continued). "Tissue differentiation-inducing non-protein coding RNA (TINCR), located on chromosome 19p13.3, is association with a variety of cancers, including breast cancer, lung cancer, gastric cancer, and liver cancer." (PMID 36385098, 2022). "Our findings enhance the current understanding of the diverse roles of TINCR in cancer biology, and the newly identified STAT3–TINCR–EGFR-feedback loop might represent a potential therapeutic target for human cancer." (PMID 33446634, 2021). "LncRNA TINCR is upregulated and contributes to the poor prognosis of many cancers." (PMID 34057016, 2021). "In the meantime, they also found that in vitro knockout of TINCR contributed to significantly decreased levels of cancer cell proliferation, while the overexpression of TINCR was conducive to cancer progression with the involvement of miR-7-5p and PI3K/Akt/mTOR signaling." (PMID 35223868, 2021). "Most of studies suggest that TINCR promotes cancer progression by sponging microRNAs." (PMID 34057016, 2021). "Therefore, the interaction proteins and molecular mechanisms of TINCR driving the cancer cell proliferation and metastasis contributing to HCC carcinogenesis have remained unresolved." (PMID 34057016, 2021). "Furthermore, LncRNA TINCR modulates cancer cell behavior in diverse kinds of cancer, for example HCC." (PMID 34057016, 2021). "TINCR expression is also reduced in prostate and lung cancers." (PMID 32681722, 2020). "So, this study has raised the possibility that TINCR could modulate the role of the Wnt signaling pathway activated by Wnt2, through sponging miR-761, thereby controlling cancer progression." (PMID 32185226, 2020). "Increased expression of TINCR is also observed in breast and gastric cancers." (PMID 32681722, 2020). "Previous studies have reported that TINCR exerts discrepant function in various cancers." (PMID 30853664, 2019). "In addition, TINCR is strongly up-regulated in human gastric carcinoma, where it was found to contribute to oncogenesis and cancer progression by regulating cell proliferation and apoptosis." (PMID 27586866, 2016). "The dysregulated expression of several lncRNAs, such as CRNDE, TINCR, and PDIA3P1, has been associated with chemotherapy resistance in several human cancers, highlighting that lncRNAs might represent attractive molecular targets for cancer treatment." (PMID 35717675, 2022). "TINCR, a lncRNA, is an unfavorable prognostic factor in NPC and mediates the lipogenesis pathway to contribute to cancer progression in NPC." (PMID 35628510, 2022). "The validation results were highly in great agreement with those in microarray, and the expression tendency of HOTAIR, TINCR, LINC00511, LINC00520, MEG3, and ZNF667-AS1 was also consistent with literature reports in other carcinomas." (PMID 31196171, 2019). "The expression levels of TINCR in 248 HCC samples and matched para-carcinoma specimens were detected by quantitative real-time RT PCR (qRT-PCR)." (PMID 28546230, 2017). "In this study, we demonstrate that TINCR is up-regulated in BCa tissues and cell lines (SW780 and 5637) and contributes to oncogenesis and cancer progression." (PMID 27586866, 2016). "Given the multiple mechanisms of action known for lncRNAs, it is not surprising that the same lncRNAs may exert dual functions in cancer, acting as either tumor suppressors or oncogenes, depending on the cancer type (H19, BANCR, TINCR, MALAT, XIST)." (PMID 35159386, 2022). "Moreover, it was also found some cancer‐specific lncRNAs, such as LINC01140, LINC00261, ABHD11‐AS1, and TINCR,58, 59, 60, 61 served as important biomarkers in other different cancer types as well." (PMID 30318850, 2018). "In the present study, we found that forced expression of TUBL promoted keratinocyte proliferation in a manner independent of the RNA secondary structure of TINCR, suggesting that promotion of cancer cell proliferation by TINCR is also likely mediated by TUBL protein rather than by TINCR RNA." (PMID 34351912, 2021).
cancer (continued). "Using Cytoscape, we were able to segregate the subnetwork of 76 genes potentially governed jointly by TINCR (65 genes) and LINC01359 (55 genes), which resulted in submodules of genes with core histone protein domains (green nodes) and involved in pathways in cancer (blue nodes)." (PMID 30959550, 2019).
head and neck tumours (1 paper, 2021). "Through online analysis of prognostic data, we also found that patients with head and neck tumours with high expression of TINCR had a better prognosis." (PMID 34187411, 2021).
TINCR also shares sentences with these, for which no sentence is quoted: diabetic cardiomyopathy (4 papers); non-small cell lung carcinoma (3); head and neck squamous cell carcinoma (2); lung adenocarcinoma (2); acute myeloid leukemia (1); autoimmune disease (1); diffuse large B-cell lymphoma (1); endocervical carcinoma (1); esophageal carcinoma (1); gallbladder cancer (1); gastrointestinal tumor (1); glioblastoma (1); ichthyosis vulgaris (1); lung squamous-cell carcinoma (1); lymphoid neoplasm (1); Miscarriage (1); oral cancer (1); ovarian serous cystadenocarcinoma (1); pancreatic adenocarcinoma (1); pancreatic cancer (1); psychiatric disorder (1); retinoblastoma (1); schizophrenia (1); stomach adenocarcinoma (1); thymoma (1); thyroid carcinoma (1); tongue squamous cell carcinoma (1); triple-negative breast carcinoma (1); uterine corpus endometrial carcinoma (1).